IL24 (interleukin 24)
Diseases named in the same sentence as IL24 in open-access papers (continued):
Sharing a sentence is not in itself a finding about the gene and the disease.
cancer (continued). "MDA-7/IL-24 protein expression is low or absent in cancer cells as compared to their normal counterparts." (PMID 31489119, 2019). "A positive colocalization signal was observed for the MDA-7/IL-24-CHC antibody pairs, but not for the MDA-7/IL-24-caveolin-1 antibody pair, thereby indicating a specific association of internalizing MDA-7/IL-24 with CHC in nonfractionated cancer cells." (PMID 31489119, 2019). "Given its ubiquitous apoptotic effect on malignant cells, the lack of an effect on normal cells, and the absence of significant side effects, IL-24 is an important candidate for cancer therapy." (PMID 30424508, 2018). "Although signaling pathways triggered by IL-24 have been the focus of intensive studies for over 20 years, the mechanisms governing cancer-specific apoptosis triggered by IL-24 are still not well understood." (PMID 30424508, 2018). "Our previous studies have shown that a non-replicating adenoviral vector expressing Interleukin 24 (Ad.IL-24) induces apoptosis selectively in cancer cells, mediated through phosphorylation of eIF2α." (PMID 29786657, 2018). "In addition, IL-24 suppresses the synthesis of angiogenic factors including FGF, VEGF, TGF-β, and IL-8 synthesized by cancer cells, in turn inhibiting the differentiation of endothelial cells." (PMID 29662489, 2018). "In order to elucidate whether miR‐203a‐3p.1 is related to cancer metastasis by down‐regulation of IL‐24, HCC cells were transfected with miR‐203a‐3p.1 mimics or IL‐24, and cell migration and metastasis were assayed with Transwell chambers." (PMID 28781949, 2017). "IL-24 is well known for its apoptotic effect in cancer cells while having no such effect on normal cells." (PMID 27271601, 2016). "Our previous studies have shown that a non-replicating adenoviral vector expressing IL-24 (Ad.IL-24) induces apoptosis selectively in cancer cells through IL-20 receptor-dependent, JAK/STAT-independent and MAPK-dependent pathways." (PMID 27271601, 2016). "Previous studies have demonstrated that enforced expression of IL-24 inhibits growth and promotes apoptosis in a broad range of human cancers without harming normal cells." (PMID 27203744, 2016). "IL-24, a member of the IL-10 family, can selectively induce apoptosis in a variety of cancer cells without affecting the normal cells in vitro, in vivo, and in a phase I clinical trial." (PMID 27322080, 2016). "Given its ubiquitous apoptotic effect on malignant cells, lack of an effect on normal cells, and absence of significant side effects, IL-24 is an important candidate for cancer therapy." (PMID 27271601, 2016). "Preclinical studies have shown that ectopic expression of IL24 induces apoptosis in cancer cells with no significant cytotoxicity to normal cells." (PMID 27528029, 2016). "An important question, which remained unresolved, is why IL-24 has the abilities to selectively induce apoptosis in a large spectrum of human cancer-derived cell lines without harming normal cells." (PMID 27271601, 2016). "Several studies indicate that mda-7/IL-24 selectively induces apoptosis in cancer cells without harming normal cells, by promoting an endoplasmic reticulum (ER) stress response." (PMID 26460950, 2015). "Importantly, MDA-7/IL-24 also showed anti-cancer “bystander” activity, since the growth of uninjected tumors was also suppressed in animals in which tumors were injected with the MDA-7/IL-24-expressing virus." (PMID 26474456, 2015). "The most notable feature of IL-24 is selectively induced growth suppression and apoptosis in various cancer cells, with no harmful effects toward normal cells." (PMID 26361755, 2015). "Initial studies conducted in our laboratory and others focused on testing IL-24 as a cancer gene therapeutic using viral and non-viral vectors and investigating the molecular mechanism of cell killing." (PMID 24377906, 2013). "The fundamental question of why IL-24 protein expression is lost in cancer cells although mRNA is detectable has not been studied." (PMID 24377906, 2013).
cancer (continued). "Since the mechanisms by which MDA-7/IL-24 suppresses Bcl-2 expression and facilitates cancer cell apoptosis have not been clarified." (PMID 22629368, 2012). "MDA-7/IL-24 is a distinctive cytokine that uniquely displays potent anti-cancer activity toward a broad-spectrum of human cancers, without provoking toxicity in normal cells or tissues." (PMID 22808125, 2012). "IL-24-siRNA completely blocks Bcl-2 ubiquitination via reversion of Bcl-2 S-denitrosylation and protects it from proteasomal degradation which confirmed the significant role of MDA-7/IL-24 in regulating posttranslational modification of Bcl-2 in cancer cells." (PMID 22629368, 2012). "We have previously shown that inhibition of NF-κB in cancer cells increases apoptosis without promoting mda-7/IL-24 production." (PMID 21931671, 2011). "In this context, it remains completely unclear how these different recombinant forms of IL-24 retain their deduced selectivity for cancer cells while healthy cells are not affected or harmed." (PMID 18074024, 2007). "Notably, the treatments altered the gene expression of several tumorigenic and immunologic mediators, including MSXI, ZRSR2, GALNTL6, IL24, and IL18R1, which may impact cancer cell behavior." (PMID 42158898, 2026). "In cancer cells, IL-24 exerts its biological effects also via non-canonical JAK/STAT pathway activation through interaction with other intracellular molecular partners, including endoplasmic reticulum (ER)–resident chaperone BiP/GRP78 and dsRNA-activated protein kinase (PKR)." (PMID 40806452, 2025). "We have shown that the adenovirus (Ad) vector expressing IL-24 (Ad.IL-24), IL-24 protein (generated from Ad.IL-24-infected cells), and adenovirus vector expressing nonsecretable IL-24 all display broad cancer-specific pro-apoptotic activity through induction of endoplasmic reticulum (ER) stress." (PMID 37444474, 2023). "Therefore, there is a clear distinction between the signaling pathways triggered by a high concentration of IL-24 followed by induction of apoptosis in cancer cells via a JAK/STAT-independent mechanism and the canonical JAK/STAT signaling pathway activation by physiological concentrations of IL-24." (PMID 37444474, 2023). "We previously created a broad-spectrum, cancer-selective and replication competent therapeutic adenovirus that embodies two of these properties, i.e., specifically reproduces in cancer cells and produces a therapeutic cytokine, MDA-7/IL-24, a “cancer terminator virus” (CTV)." (PMID 33670594, 2021). "With very few exceptions, most normal and cancer cells contain either IL-20R1, IL-20R2 and/or IL-22R1 receptors, which can form dimeric receptor complexes, allowing them to respond to exogenous MDA-7/IL-24 resulting in autocrine induction of MDA-7/IL-24 production, the autocrine/paracrine loop." (PMID 35008495, 2021). "IL24 mRNA is known to have an apoptotic effect on cancer cells but not on noncancer cells." (PMID 33014054, 2020). "Since cancer patient’s immune system is intact, and ZD55-IL-24 can infect, directly lyse and express exogenous IL-24 in human cancer cells within patient’s tumors, we thus speculate that all the antitumor pathways are probably able to act synergistically in patients." (PMID 33257647, 2020). "IL-24 can be used to treat various cancers but has no obvious adverse effects on normal cells." (PMID 32318337, 2020). "Further analysis suggested that modulation of angiogenesis-related genes (including ANGPTL4, FN1, HSPG2, SRPX2, KLK5, L1CAM, Prr22, FOXJ1, IL24, and TRIM54) potentially contributes to anlotinib resistance, as anlotinib is a multi-targeted anti-angiogenesis drug for cancer therapy." (PMID 31572680, 2019). "But IL‐24 regulation by miRNAs in cancer has lacked investigation." (PMID 28781949, 2017). "Moreover, we have established that production of ceramide and induction of ER stress following Ad.IL-24 infection or IL-24 treatment occurs specifically in cancer but not in normal cells." (PMID 27271601, 2016).
cancer (continued). "Importantly, no pro-inflammatory genes (with the exception of IL24) and pathways were affected, cancer-related pathways were modulated minimally and only a low AhR-mediated activity was found at sub-cytotoxic concentration of DEP extracts." (PMID 27827897, 2016). "Thus, our results represent important proof-of-principle studies regarding the relevance of MDA-7/IL-24 in immune competent animals and suggest that MDA-7/IL-24 might serve as an appropriate anti-cancer agent in combination with other therapeutics." (PMID 26474456, 2015). "Interleukin 24(IL-24), also called melanoma differentiation associated gene-7(MDA-7), is a unique member of the IL-10 gene family, that displays a selective induction of cancer specific apoptosis without deleterious effects on the normal cells." (PMID 22629368, 2012). "By using cell lines deficient of individual components of the Jak/STAT pathway or by using Jak inhibitors it was demonstrated that initial IL-24-induced apoptosis of cancer cells is independent of Jak/STAT signaling pathways and thus independent of receptor engagement." (PMID 18074024, 2007). "Thus, we generated a recombinant nonlytic NDV virus expressing IL-24, and the recombinant virus could greatly enhance the prophylaxis and therapeutic effects against cancer." (PMID 31338417, 2019). "The results showed that the IL24 mRNA was highly expressed in HNSCC and its subgroups and had the ability to distinguish between cancer and noncancer tissues." (PMID 33014054, 2020). "For most surrogate peptides measured, the cancer urine showed higher median L/H values than non-cancer urine; while for several others (CRISP3, CXL14, IL24 and SFRP4), a lower or equal median L/H value in cancer vs. non-cancer was found." (PMID 29254211, 2017). "Interestingly, MSC spheroids were shown to selectively reduce the viability of cancer cell lines but not that of noncancer-derived immortalized cell lines in an IL24-dependent mechanism, suggesting that MSC spheroids might be utilized in novel cancer therapeutics." (PMID 26649054, 2016). "Also, MDA-7/IL-24 upon internalization in cells interacts and up regulates the chaperone protein BiP/GRP78 to induce cancer-specific cell death without harming normal cells." (PMID 31489119, 2019).
infection (51 papers, 2007 to 2025). The state of being infected such as from the introduction of a foreign agent such as serum, vaccine, antigenic substance or organism. "In contrast, Staphylococcus aureus skin infections in mice are associated with increased local IL-24 expression, and this cytokine was implicated in decreased levels of the pro-inflammatory cytokines IL-1β and IL-17 at sites of infection." (PMID 30825881, 2019). "We next identify a significant association of IL-19 and IL-24 secreting T cells with asymptomatic infection." (PMID 24699268, 2014). "Recent data from a mouse model of S. aureus, however, clearly reveals an important immuno-modulatory role for IL-19 and IL-24 in suppressing IL-1β and IL-17 dependent effector pathways and promoting susceptibility to infection." (PMID 24699268, 2014). "IL‐24 based therapy has also proven effective in the management of infection by intracellular pathogens, especially Mycobacterium tuberculosis (Mtb) infection." (PMID 40338095, 2025). "EV-A71 infection enhanced IL-19 levels from 1 to 5 d.p.i., with significant increases on 3 and 5 d.p.i., and slightly increased IL-20 levels on 3 and 5 d.p.i. and IL-24 levels on 1 d.p.i.." (PMID 41550952, 2025). "In vivo, murine models of H5N8 and H5N1 influenza infection demonstrated marked upregulation of IL-24 during the course of infection." (PMID 40943325, 2025). "In conclusion, it can be stated that IL‐24 demonstrates a dual function in immune system response against bacterial and viral infections, with its role being contingent upon the specific infection model being investigated." (PMID 40338095, 2025). "IL‐24 production is induced during infection with Staphylococcus epidermidis and S. saprophyticus, and IL‐24 plays an immunosuppressive role during S. aureus infection." (PMID 40338095, 2025). "These regulation of parasite antigen-specific IL-19 and IL-24 expressing CD8+ T cells are more dependent on the stage of the infection than on IL-10, IL-1β, and IL-23 as observed in the regulation of CD4+ T cell response." (PMID 34603287, 2021). "Infection with either Ad.5-CTV or Ad.5-TCTV at 25 or 50 pfu increased the MDA-7/IL-24 transgene protein expression." (PMID 33670594, 2021). "IL-24 induces innate defense mechanisms in epithelial tissues, during infection and inflammation, and restores tissue homeostasis." (PMID 27271601, 2016). "The localization of LC3 in autophagy vacuoles in the IL-24 treated KB cells was determined by transient transfection of a plasmid expressing green fluorescent protein fused with LC3 (GFP-LC3) followed by infection." (PMID 26361755, 2015). "In KB cells, infection with AdLTR2EF1α-IL-24 induced a high level of apoptosis, whereas the AdLTR2EF1α-vec did not have such effects." (PMID 26361755, 2015). "SG600-IL-24 infection induced higher levels of IL-24 mRNA and protein expressionin the normal liver cell line L02, as well as in the HCC cell lines of differingmetastatic potential, HepG2, MHCC97L, and HCCLM3." (PMID 22569271, 2012). "Such is the case of the interleukin-24 (IL-24) gene homolog found in the Yaba-like disease virus (a poxvirus), which appears to reduce its virulence upon infection." (PMID 23227424, 2012). "Infection with SG600-IL-24 displayed CMV-driven IL-24 production inboth normal cells L02 and in the 3 HCC cell lines." (PMID 22569271, 2012). "In response to P. aeruginosa, genes associated with IFN-γ response to infection (CXCL10, IL-24, IFNγR2) and other mediators of anti-infectious responses (CSF2, MMP1, MMP3, TLR2, S100 calcium-binding proteins A) were markedly up-regulated in wild-type TG cells." (PMID 19399182, 2009). "Depending on the multiplicity of infection (moi), the efficient delivery of IL-24 by an adenoviral expression system is likely to induce UPR or ER stress and several reports have already confirmed this notion." (PMID 18074024, 2007). "Notably, Il24 exhibited the greatest and most persistent response to the infection among the family members." (PMID 38752989, 2025).
infection (continued). "Thus, the aim of this study is to investigate the association of IL-24 serum levels on the further course of SARS-CoV-2 infections in moderate, severe and critical infections." (PMID 40943325, 2025). "Fourth, while we correlated IL-24 levels with markers of kidney/liver function, we did not examine the exact mechanisms underlying the modulation of IL-24 during infection." (PMID 40943325, 2025). "Finally, expression of interleukins in general and CXCL12 specifically demonstrated infection and PM-specific patterns characterized by unique upregulation of IL24 following Winter PM and IL11 and CXCL12 upregulation following Spring PM co-exposure." (PMID 40671793, 2025). "Thus, parallel to innate immune sensing of pathogens to resolve infections, epithelial stem cells sense injury signals to orchestrate IL-24-mediated tissue repair." (PMID 37098344, 2023). "However, analogous to the role of IFN in resisting pathogen infection, IL-24 coordinates a pro-angiogenetic repair and proliferation program to restore tissue integrity and homeostasis." (PMID 37098344, 2023). "While the delayed production of IL-24 by activated astrocytes is similar to the production of IL-10 and IL-19 by these cells following infection and is consistent with a role in infection resolution, we have directly assessed the effect of this cytokine on inflammatory astrocyte responses." (PMID 30825881, 2019). "Furthermore, in the same study, it was demonstrated that IL-24 increases infection severity, consistent with an immunosuppressive role for this IL-10 family member." (PMID 30825881, 2019). "As such, the present study supports the notion that IL-24 production by astrocytes and/or infiltrating leukocytes could function to regulate or resolve CNS inflammation following infection in order to limit neuronal damage." (PMID 30825881, 2019). "However, the injection of a plasmid leading to the overexpression of IL-24 into animals prolonged survival rates after infection with Salmonella typhimurium." (PMID 29967613, 2018). "Infection of mice with Citrobacter rodentium leads to increased IL-19, IL-20, and IL-24 expression." (PMID 29967613, 2018). "Interestingly, IL-24 is induced locally by S. aureus, inhibits IL-1β and IL-17 production, leading to more severe infection and reduced neutrophil recruitment." (PMID 27271601, 2016). "In addition to playing a protective role in the host defense in epithelial tissues during infection, IL-24 is activated during Staphylococci infections of the skin." (PMID 27271601, 2016). "Alternatively, production of progeny virus might have entered the circulation and caused secondary infection of distant tumors, resulting in production of MDA-7/IL-24." (PMID 26474456, 2015). "Thus, the frequency of T cells expressing IL-10, IL-19, IL-24 and IL-26 are all decreased upon curative treatment, in contrast to that seen in those who continued to harbor infection." (PMID 24699268, 2014). "This is further corroborated by the fact that filarial - antigen stimulation of PBMC cultures also resulted in significantly increased levels of total IL-19 and IL-24 in filarial infected individuals when compared to those with pathology and inactive infection." (PMID 24699268, 2014). "Thus, the regulation of IL-10, IL-19 and IL-24 expression in filarial infection is dependent on the presence of active infection and therefore, curative treatment ablates the increase in the frequency of these predominantly regulatory T cells." (PMID 24699268, 2014). "Infection of SKOV-3 cells with the mda-7/IL-24 siRNA lentivirus reduced apoptosis induced by NSAIDs by 40–70% relative to the control lentivirus, further supporting the notion that NSAID-mediated apoptosis is at least partially dependent on mda-7/IL-24 induction." (PMID 21931671, 2011).